IGF1 (insulin like growth factor 1)
Diseases named in the same sentence as IGF1 in open-access papers (continued):
Sharing a sentence is not in itself a finding about the gene and the disease.
cancer (continued). "Moreover, poorly-differentiated cancer thyrospheres produce a high amount of both IGF-1 and IGF-2." (PMID 30513575, 2018). "Thus, our results suggest that CD215+ myeloid cells respond to IL-15 and promote cancer progression, and IGF-1 may be an important candidate that IL-15 facilitates tumor growth." (PMID 29255466, 2017). "Thus, this is the first adequately powered randomized clinical trial to test in nonobese humans the long‐term effects of CR on the IGF‐1 axis and other growth factors implicated in the pathogenesis of cancer." (PMID 26443692, 2016). "We reviewed human data to obtain the following preliminary conclusions concerning insulin/IGF-1 modulation in humans: (i) DR could be considered as a supportive treatment during cancer therapy due to its probable antitumor effects, and due to its beneficial effects on human metabolism." (PMID 26878387, 2016). "On one side, as insulin is an anabolic factor that normally blocks protein breakdown and promotes protein synthesis;159, 160 insulin resistance (and similarly IGF-1-resistance) might promote muscle wasting, hence, amino acid mobilization into the circulation, potentially fueling cancer." (PMID 26900952, 2016). "Next, we addressed whether adipocytes may control CCL5 and IGF-1 production by cancer cells." (PMID 27027351, 2016). "Some epidemiological studies in healthy adults without GHD have suggested associations between serum IGF1 concentrations in the upper part of the normal range or above and some forms of cancer, and between serum IGF1 concentrations in the lower part of the normal range and cardiovascular disease." (PMID 26563978, 2016). "Additionally, human IGF-1 receptor gene polymorphisms are associated with exceptional longevity, and recently, Barzilai and colleagues have shown that low plasma IGF-1 concentrations predict survival in long-lived people, specifically in women with a history of cancer." (PMID 25902704, 2015). "However, cancer-related mortality is increased only in acromegalic patients with poorly controlled disease, as assessed by high circulating levels of Insulin-like-Growth-Factor 1 (IGF-1)." (PMID 25962899, 2015). "Therefore, decreased IGF-1 can indicate new strategies for cancer prevention." (PMID 26131344, 2015). "Controlling the levels of GH and IGF1 may therefore be an important strategy to prevent cancer." (PMID 26682276, 2015). "In addition to direct contributions to each of these stages, IGF-1 may promote cancer indirectly, through interactions with oncogenes and tumor supressors, with other hormones (particularly sex steroids in breast and prostate cancers) and with IGFBPs." (PMID 25333772, 2014). "In addition, BMH may represent a niche for homing of cancer cells and the secretion of IGF-1 which provide protection while promoting their proliferation and chemoresistance." (PMID 25095896, 2014). "However, specific associations between hyperglycemia, insulin, IGF-1, IGFBP3 and the risk of cancer among people with type 2 diabetes remain unclear." (PMID 23405181, 2013). "Although these findings suggest an insulin-independent, direct anti-tumoral activity for metformin, it remains unknown whether cancer cell-autonomous alterations that are known to drive insulin/IGF-1-independent, DR-resistant tumors preclude the anti-cancer activity of metformin." (PMID 23986086, 2013). "IGF-IR regulation of β1 integrin expression, is critical in the context of reported alterations in the IGF-1 axis signaling and expression during cancer progression, and implies that variations of the levels of one receptor may influence the profile of other receptors." (PMID 24130778, 2013). "Furthermore, receptors for insulin and IGF-1 are expressed in most cancer cells." (PMID 23431471, 2013). "Thus, the association between IGF1, IGF2, and IGFBP3 and cancer risk could be evaluated on the molecular level." (PMID 22347413, 2012). "In addition, lycopene inhibits the mitogenic action of IGF-1 in human cancer cells." (PMID 22418926, 2012).
cancer (continued). "To identify the paracrine factors responsible for T47D carcinoma cell growth stimulation we treated the co-cultures with neutralizing antibodies to eleven factors implicated in stroma-carcinoma interactions (FGF-2, HB-EGF, Heparanase-1, HGF, IGF-1, IGF-2, MT1-MMP, PDGF, SDF-1, TGF-β1, and Wnt-1)." (PMID 23056402, 2012). "1,25-dihydroxyvitamin D3 has been shown to increase expression of IGFBP-3 possibly by attaching to the BP-3-vitamin D response element (VDRE) on the IGFBP-3 promoter suggesting that some of the cancer promoting effects of IGF-1 may be modified by vitamin D via changes in IGFBP-3 levels." (PMID 22216097, 2011). "Insulin may also indirectly promote cancer development via IGF-1." (PMID 21773024, 2011). "The possible reason may be that IGF-1 pathway involves in tumorigenesis of this two cancer types." (PMID 20642846, 2010). "It is tempting to speculate that the antiapoptotic effects of IGF-1 hinder cancer therapies that target other PTKs, and that the antineoplastic effects observed when blocking a PTK may be significantly underestimated if examined only under conditions where IGF-IR is fully functional." (PMID 15150607, 2004). "KD induces ketosis, reducing inflammation and glucose supply to cancer cells, and STS lowers blood glucose and IGF-1 levels to sensitize tumors to chemotherapy." (PMID 40813374, 2025). "IGF‐1 treatment activates IGF/IGF‐1R signaling in HBV‐positive HCC cells, increasing expression of cancer stemness markers like nanog homeobox (NANOG) and octamer‐binding transcription factor 4 (OCT4)." (PMID 40060195, 2025). "Increased SHH signaling in PDAC induces insulin-like growth factor 1 (IF1) expression and growth arrest-specific (GAS6) expression, leading to Akt signaling activation in cancer cells." (PMID 40136652, 2025). "The distinct potential molecular functions of IGF1 and E peptides, particularly those of its various classes in EC, should be investigated, and their discovery may yield new insight into this hormone-dependent cancer pathogenesis, especially endometrioid subtype." (PMID 39796756, 2025). "The search terms included ‘irisin’ or ‘Fndc5’ with ‘cancer’, ‘tumour’, ‘neoplasia’, ‘oncogenesis’, ‘cell proliferation’, ‘apoptosis’, ‘metastasis’, ‘epithelial-mesenchymal transition (EMT)’, ‘IGF-1’, and ‘PI3K/Akt/mTOR pathway’." (PMID 41002741, 2025). "Core genes with a higher DC (> 8), EC (> 0.06), LAC (> 2.0), BC(> 200), and NC(> 0.3) in the enriched modules were also expressed differentially in TCGA‐CHOL data (36 tumor samples and 9 adjacent cancer samples), including FGF2, IGF1, CAV1, SPON1, and ADAMTS4." (PMID 40304434, 2025). "Metformin, a cornerstone in T2DM management, has shown promise in reducing PC risk and improving outcomes by lowering insulin and IGF-1 levels and activating AMP-activated protein kinase pathways, thereby inhibiting cancer cell growth." (PMID 40732935, 2025). "Three therapeutic monoclonal antibodies (AXL1717, MEDI-573, and BI836845) that neutralize IGF1/2 have the potential to counteract IGF2 repression of the immune reaction to cancer and its promotion of chemoresistance in cancer." (PMID 41007637, 2025). "Studies have shown that fasting can reduce glucose and insulin-like growth factor 1 (IGF-1) levels, both of which are critical for cancer cell metabolism and growth." (PMID 40296920, 2025). "Some studies report increased affinity of certain IGF1 isoforms to IGF1R, implicating them in cancer development." (PMID 39796756, 2025). "This reduction in IGF-1 levels leads to decreased activation of the PI3K/AKT and RAS/RAF/ERK pathways, which are crucial for cancer cell survival and proliferation." (PMID 39940361, 2025). "Its levels were found to be significantly reduced in cancer cells, and in silico analysis revealed that the 3′-UTR of IGF-1R was among the predicted putative targets of the IGF-1 pathway." (PMID 41153350, 2025).
cancer (continued). "Specifically, C-peptide and IGF-1 levels are elevated in patients with SCLC and advanced stages of the disease, hinting at a connection with more aggressive cancer forms." (PMID 39044884, 2024). "In another study, IGF1 (insulin like growth factor 1) signaling activates mitochondrial biogenesis and mitophagy via BNIP3 expression to sustain cancer cell growth and viability." (PMID 38447939, 2024). "The insulin-like growth factor (IGF) axis, particularly that of IGF-1 and its binding protein, insulin-like growth factor-binding protein-3 (IGFBP-3), is another area of interest in cancer research." (PMID 39200386, 2024). "Elevated levels of insulin and insulin-like growth factor-1 (IGF-1) can promote cellular proliferation and inhibit apoptosis, further contributing to cancer development and progression." (PMID 39379738, 2024). "In cancer, since IGF-1 is a potent cytoprotective signal, IGF-1/IGF-1R activity has been long ago established as pro-tumorigenic." (PMID 39638246, 2024). "Excessive activation of ERs has been shown to upregulate genes responsible for synthesizing growth factors, such as insulin-like growth factor-1 (IGF1) and epidermal growth factor (EGF), both of which promote the growth of cancer cells." (PMID 39659890, 2024). "The IGF-1R is activated by binding to the growth factors IGF-1 and IGF-2 and overexpressed in various cancers." (PMID 38835346, 2024). "Here we have evaluated the expression of IGF1, CCL5, IL-8, VCAN and RTN4 in peritumoral AT of women with BC, to investigate their potential role as markers of cancer progression." (PMID 39501160, 2024). "Insulin receptor (IR) and insulin-like growth factor-1 (IGF-1R) are both critical in the progression of cancer, particularly in tumorigenesis and the development of cancer drug resistance due to cross-talk between IGF-1R and IR signaling pathways." (PMID 39335147, 2024). "This study explores the anti-cancer effects of linsitinib and metformin on OVCAR3 cells by the suppression of the IGF-1 signaling pathway by siRNA-mediated IGF-1 gene silencing." (PMID 39596005, 2024). "Both IGF-1 and IGF-2 have demonstrated the ability to stimulate cancer cell proliferation and metastasis." (PMID 39301314, 2024). "The authors postulated a potential correlation between different cancer subtypes and the inflammatory adipose microenvironment rich in IL-6 and TNF-alpha, along with heightened levels of IGF-1 observed in obese patients." (PMID 38611106, 2024). "A variety of IGF-1/IGF-1R inhibitors have entered clinical development in the cancer field, including IGF-1-R tyrosine kinase inhibitors (including sorafenib) and mAbs against IGF-1-R and IGF-1." (PMID 39796700, 2024). "The axis represented by IGF1 and its receptor, the insulin-like growth factor 1 receptor (IGF1R), is deregulated in many cancer cell types." (PMID 38420122, 2024). "In the context of OSCC, preclinical studies indicate that metformin inhibits mTORC1 activity through pathways involving IGF1 and IGF2, contributing to reduced cancer cell proliferation." (PMID 39272875, 2024). "High levels of glucose and insulin can increase the activity of various growth factors, such as insulin-like growth factor-1 (IGF-1), which can stimulate the growth and survival of cancer cells." (PMID 39048990, 2024). "During this action, transforming growth factor, calcium, bone morphogenetic proteins, fibroblast growth factors, and insulin-like growth factor-1 (IGF-1) are all produced, encouraging cancer cell proliferation and survival." (PMID 39574432, 2024). "The availability of IGF-1 and IGF-2 to tumor cells from both endocrine sources and autocrine/paracrine production further underscores the importance of this pathway in cancer progression." (PMID 39273251, 2024).
cancer (continued). "Other soluble factors like transforming growth factor beta (TGF-β) and insulin-like growth factor 1 (IGF-1) also modulate the Hippo pathway, impacting cancer development and progression." (PMID 39431199, 2024). "Plasma growth factor levels were analyzed in surgical cancer patients, including hepatocyte growth factor (HGF), epidermal growth factor (EGF), and insulin-like growth factor-1 (IGF-1)." (PMID 38067195, 2023). "Molecules like pro-inflammatory cytokines, transcription factors, insulin-like growth factor 1 (IGF-1), kinases, proteins, and abnormal expression of angiotensin II (Ang II) are involved in the complex process of cancer cachexia." (PMID 38067294, 2023). "As IGFBP-2 is the main binding protein and inhibitor of IGF-1 and therefore inhibits its pro-proliferative action, it would be logical for IGFBP-2 to be downregulated in patients with cancer." (PMID 38137390, 2023). "For instance, as cancer cachexia advances, both circulating IGF-1 and muscle IGF-1 gene expression tend to decrease, thereby contributing to the decrement of protein synthesis." (PMID 37755304, 2023). "Secreted inflammatory cytokines in cancer cells, including IL-22, IL-6, IL-8, IL-4, IL-1β, HGF, IGF-1, EGF, G-CSF, TNF-α, VEGF, and IL-11, can confer the promotion of chemo- and radioresistance." (PMID 38140352, 2023). "αKlotho has been identified as a tumor suppressor and inhibits the insulin-like growth factor 1 (IGF1), FGF, and Wnt/β-catenin pathways; yet, the mode of action of αKlotho in cancer is a matter yet to be confirmed." (PMID 38069256, 2023). "We identified distinct genes including KLK4, FN1, PBOV1, TPM2, and FLNA which are known to be involved in PCa pathways along with IGF1, TPD52, and SRSF1 that are involved in different cancer pathways." (PMID 37218885, 2023). "Given the differences between IRS1/2 and IRS4 at the molecular level, knowledge of the signaling pathways controlled by IRS4 may enable the design of new drugs for the treatment of cancer without causing deleterious effects on the regulation of insulin and/or IGF1 signaling cascades." (PMID 37760618, 2023). "This hormone arouses cancer growth by decreasing insulin-like growth factor (IGF) binding protein, increasing the bioactivity of IGF-1, and changing the metabolism of the sex hormone." (PMID 37069525, 2023). "It was shown that activation of IGFR/PI3K/AKT pathway by IGF1 resulted in phosphorylation of FOXO1/3 in cardiac stem cells, myotubes or cancer cells." (PMID 37985893, 2023). "Genes whose median expression was below the threshold in more than half of the cancer types were common in cohorts A and B (ADGRB1, IGF1, RPRM, TP53AIP1)." (PMID 36964217, 2023). "Conversely, the proteoglycans in cancer pathway, containing genes which code for matrix metalloproteinases (MMP), WNT signaling molecules, and growth factors such as IGF1 and FGF2, is prominent in bexarotene differential expression analysis but not MSU-42011." (PMID 36901727, 2023). "One of the genes most significantly overexpressed in the poorest-prognosis CGS1 subtype was IGF1, a ligand for IGF1R that is a known potential therapeutic target for many cancers." (PMID 37674200, 2023). "This review summarizes the contribution of IGF-1/IGF-1R signaling to the development of PCa and highlights the relevance of IGF-1/IGF-1R signaling in potential cancer therapies." (PMID 36831629, 2023). "Considering the function of IGF1/IGF1R in cell differentiation, proliferation, and apoptosis, its activation is correlated with initiation, progression of cancer, and poor survival." (PMID 37284192, 2023). "Several reports suggest that excessive intracellular ROS production trigger HIF-1α mediated apoptosis in cancer cells via activation of IGF-1 binding protein 3 (IGFBP-3) and inhibition of IGF-1 signaling." (PMID 37560308, 2023).
cancer (continued). "This phenomenon is particularly important in cancer cells, wherein TXNIP is often epigenetically silenced, thereby leading to a potentially amplified effect of both IGF1 and insulin on mitosis." (PMID 36291127, 2022). "The IGF-1 pathway is regarded as a key promoter of tumor progression, and IGF-1 receptor inhibitors can contribute to cancer therapy." (PMID 35626156, 2022). "The most active small molecule (BM001) inhibited both the GH/IGF1 axis and cell proliferation with an IC50 of 10‐30 nM of human cancer cells." (PMID 35966052, 2022). "In a physiological setting, IGF-1 inhibits apoptotic effects and supports cell survival, whereas, in pathophysiological conditions, IGF-1 can enhance cancer progression or increase the number of adipocytes." (PMID 36498723, 2022). "The crosstalk of progesterone and PR with IGF-1 signaling via IRS2 promote growth of breast and cervical cancer cells." (PMID 35816477, 2022). "A recent study in the field of cancer biology performed with mouse embryonic fibroblasts identified IGFBP5 as a secreted, mTORC1 downstream effector protein that inhibits the function of IGF-1." (PMID 35513854, 2022). "IGF-1 receptor (IGF-1R) inhibitors prevent binding of IGF-1 to IGF1R and subsequently inhibit down stream signaling, including PI3K/Akt pathway, exerting antitumor activity and being potential targets for cancer treatment." (PMID 35126480, 2022). "In this study, the IGF-1 receptor inhibitor AG1024 increased the response of resistant cancer cells to docetaxel and decreased the expression of TUBB2B, highlighting the potential of targeting the IGF-1 axis as a novel therapeutic strategy." (PMID 36017326, 2022). "hMSCs also play a role in cancer progression by releasing angiogenic factors, such as IGF-1, SDF-1, and PDGF, which promote tumor neovascularization, enhance tumor engraftment, and suppress immune responses to cancer cells." (PMID 36406002, 2022). "Insulin-like growth factor-1 (IGF-1) and the IGF binding protein 1 (IGFBP-1) expressions have been shown to play a vital role in cancer biology, including endometrioid endometrial cancer (EEC)." (PMID 36544136, 2022). "In another study, it was seen that melatonin treatment of breast cancer cells causes reduced VEGF-A protein expression and increased IGFBP-3, IGFPB-6, IGF-1, IGF-1R proteins in those cells and results in suppression of cancer cell growth." (PMID 36581900, 2022). "By regulating the bioavailability of the type-1 IGF receptor (IGF1R) ligands, IGF-1 and IGF-2, the IGF binding proteins (IGFBP-1 to -6) play essential roles in cancer progression." (PMID 35597813, 2022). "When relevant, the roles of IGF1 and IGF2 in cancer biology will be compared to those of the closely related insulin molecule." (PMID 36479090, 2022). "The expression of components of several cancer-related signaling pathways, such as Mammalian Target of Rapamycin (MTOR), PI3K/AKT, Insulin-like Growth Factor-1 (IGF-1) and Epidermal Growth Factor Receptor (EGFR) pathways are frequently disturbed in LUAD." (PMID 36446361, 2022). "Increased gene levels of VEGF, FGF, FGF7, IGF1, and IGF2, known for their proliferation-promoting effects in endothelial, fibroblasts, and cancer cells, were also detected." (PMID 36010901, 2022). "Moreover, the obtained data suggested that the combination therapy is more efficient compared to everolimus administration alone, since octreotide LAR can decrease IGF-1 levels in patients with malignant tumors, thus reducing everolimus resistance (IGF-1 upregulation could lead to it)." (PMID 36077529, 2022). "The expression of both IGF1 and IGF-1R within the same cancer confirms the existence of an autocrine–paracrine signalling loop of RCC cell stimulation." (PMID 35328822, 2022). "It was found that most cancer types showed a higher IGF-1/IGF-1R alteration frequency and the expression of IGF-1 and IGF-1R served as the prognostic factor in some cancer types, including BLCA and LAML upon both Cox and KM survival analyses." (PMID 34804946, 2021).